S100A4 (S100 calcium binding protein A4)
Diseases named in the same sentence as S100A4 in open-access papers (continued):
Sharing a sentence is not in itself a finding about the gene and the disease.
tumor (continued). "The reduction of S100A4 and MMP9 was confirmed by immunohistochemistry of tumor tissue samples." (PMID 22878175, 2012). "We suggest a mechanism in which RANTES, by mediating S100A4 release from stroma cells into the tumor milieu, by a mechanism not affecting the S100A4 gene expression enhances the metastatic capability of tumor cells." (PMID 20442771, 2010). "We documented an increase in the secretion of murine, but not human S100A4 into the MCF7S1 + HMF3s tumour microenvironment." (PMID 20723242, 2010). "The prediction of factors in metastatic vs. non-metastatic tumor cells able to stimulate the release of S100A4 from fibroblasts and other tumor composing cells was made previously." (PMID 20442771, 2010). "Furthermore, we suggest that RANTES-mediated S100A4 secretion induces the upregulation of cytokines (including RANTES), the production of FN, the stimulation of cell motility, and tumor metastases in vivo." (PMID 20442771, 2010). "The reduced tumour size of MDA/RLN2 xenografts is potentially a combined result of the observed reduction in cell proliferation and the lack of an angiogenic stimulus by S100A4 secreted from the tumour cells." (PMID 18718015, 2008). "No tumour samples were completely unmethylated at S100A4; however, 7 out of 41 (17%) of tumours displayed reduced levels of methylation compared to the normal cerebellum." (PMID 17579622, 2007). "Transgenic mouse studies have demonstrated that S100A4 by itself is not able to initiate tumours or induce metastatic effect in normal rodent cells." (PMID 16265347, 2005). "Among the four primary PTC samples with negative S100A4 staining, strong staining was observed in two matched lymph node metastasis tumour tissues." (PMID 16265347, 2005). "This indicates that expression of S100A4 only in tumour cells is not sufficient for stimulation of tumour growth and metastasis, and implicates S100A4 expressing host-derived stroma cells as the main source of metastasis-stimulating activity of S100A4." (PMID 15900299, 2005). "S100A4 immunostaining was detected in 24 out of 28 (86%) PTC specimens: 21 with diffuse staining (staining was present in more than 25% of tumour cells) and three with focal staining (staining was present in <25% of tumour cells)." (PMID 16265347, 2005). "The mechanisms by which S100A4 sensitizes the tumor cells to apoptosis induction are not completely elucidated." (PMID 15318945, 2004). "S100A4 immunoreactivity demonstrated a significant correlation with high histological grade (P=0.030), with only five of 22 (23%) of the S100A4 negative tumours described as a grade III tumour, compared to 12 of 22 (55%) of the S100A4 positive tumours." (PMID 12439718, 2002). "S100A4 staining was not correlated to the patients' ages at time of presentation, PgR, lymph node involvement or tumour diameter." (PMID 12439718, 2002). "The staining of normal tissue was not assessed further, though it was observed that tumours expressing high amounts of S100A4 protein also showed stronger immunoreactivity in the corresponding normal tissue." (PMID 12439718, 2002). "Specifically, in FOXL2+COL1A1− cells, we examined expression of other AGCT tumor markers such as SF1, calretinin, and inhibinα, whereas in FOXL2+COL1A1+ cells, we also examined expression of stromal markers, including αSMA, vimentin, S100A4, PDGFRa, PDGFRb, and FAP." (PMID 41042551, 2025). "Through single-cell data and in vitro experiments, we found that S100A4 did not directly promote the proliferation of tumor cells, but it could enhance the expression of PD-L1 in tumor cells, thereby increasing their immune escape capabilities." (PMID 40772225, 2025). "In terms of subset functional phenotype, S100a4+ alv-macro enriched for fatty acid metabolism held restricted M1-like and phagocytosis capacities at the AAH stage but exhibited M2-like, angiogenesis, and immunosuppressive features, creating a permissive environment for neoplasia." (PMID 40658605, 2025).
tumor (continued). "After TFF3 depletion, the expression of M2 markers (CD163, CD206, ARG-1, and IL-10) and S100A4 and S100A8 were remarkably downregulated, which confirmed our hypotheses that iCCA cells induce the M2 phenotype and pro-tumor polarization of resident macrophages by secreting TFF proteins." (PMID 39256888, 2024). "Similarly, Smad4 deletion in S100A4+ cells down-regulated the expression of M1-like factors such as iNOS and IL-12 and up-regulated the expression of M2-related genes such as Arg1 and IL-10 in CRC tumor tissues." (PMID 39664586, 2024). "Furthermore, we also observed a strong correlation between CRELD2 levels and those of the CAF marker S100A4, suggesting that CRELD2 may also be involved in establishing a tumor‐promoting CAF phenotype in cSCC." (PMID 38979935, 2024). "Additionally, neutrophils isolated from lungs within metastatic 4T1 tumor cells show higher expression of ApoE and S100A4 compared with neutrophils from the lungs of mice without tumors." (PMID 39695088, 2024). "Among the different proteins, S100A4 is considered a risk factor for PC, which does not express in normal tissues but is highly expressed in PC cells and related to the tumor-node-metastasis (TNM) staging and tumor size in PC." (PMID 38976715, 2024). "However, these previous studies do not discuss the interaction between CTLA4 + T cells and S100A4 in the tumor microenvironment of TNBC." (PMID 37838657, 2023). "Furthermore, the difference in the ratio of the myofibroblast area to tumor area was not significant among the S100a4-Cre; Ext1f/f and control mice." (PMID 36809261, 2023). "Interestingly, S100A4(+)/HIF-1α(+) GBM cells were found near non-Ps perinecrotic lesions, whereas S100A4(+)/HIF-1α(−) tumor cells were located at the adjacent vascular-rich areas." (PMID 35392912, 2022). "However S100A4 may also highlight tumour cells that have undergone epithelial-mesenchymal transition (EMT), and the overlap between αSMA and S100A4 in stromal fibroblasts is minimal." (PMID 36358721, 2022). "Similarly, therefore, we suggest that S100A4-driven alteration of preexisting vasculature may play a critical role in GBM progression, perhaps by accessing an alternative tumor blood supply in the presence of VEGFA." (PMID 35392912, 2022). "Interestingly, in our study, we showed that both mRNA and protein expression of S100A4 were significantly higher in tumor tissues compared with non-tumor tissues." (PMID 33815482, 2021). "Moreover, exosomal S100A4 could induce expression of osteopontin (OPN), along with other tumor metastasis/stemness-related genes." (PMID 34035222, 2021). "However, there have been no reports dissecting the intra- and extracellular roles of S100A4 in tumor cells." (PMID 33549040, 2021). "Moreover, in vivo mouse model studies could demonstrate that the depletion of S100A4+ stroma cells, including mainly fibroblasts and macrophages, within the TME of HCC, reduced stemness of the tumour, and inflammation." (PMID 32722137, 2020). "S100A4, cathepsin B, cyclin B1, Annexin A2, S100A10, TRIM21, 14-3-3 ζ/δ, and Ezrin may hence participate in tumor invasion depending on the grade of human CRCs, and protein upregulation during lymph node metastasis also suggests a positive correlation with metastasis in human CRCs." (PMID 32154176, 2020). "Many kinds of cells including fibroblasts, immune cells, and cancer cells can produce S100A4, which are released into the extracellular space in response to various stimuli such as activated normal T cell expression and secreted factors (RANTES) produced by the tumor cells." (PMID 32366023, 2020). "MCA205 and LLC cells, but not B16F10 tumor cells, expressed the S100A4 protein." (PMID 29556233, 2018). "Moreover, S100A4 is secreted from both tumor and non-malignant cells and exerts extracellular effects regulating, in particular, angiogenesis, cell migration and cardiomyocyte differentiation." (PMID 28935867, 2017).
tumor (continued). "Moreover, S100A4 is secreted from both tumor and non-malignant cells and exerts extracellular effects regulating cell mobility, invasion, and angiogenesis by interacting with annexin II, RAGE, and heparan sulfate proteoglycans." (PMID 28935867, 2017). "Also, RNAi-based S100A4 could directly reduce the expression of VEGF and MMP-9, and lead to a decrease in ATC cell invasion and tumor angiogenesis." (PMID 29069865, 2017). "Many kinds of cells including fibroblasts, immune cells, and cancer cells can produce S100A4 which is released into the extracellular space in response to various stimuli such as activated normal T cell expressed and secreted factors (RANTES) produced by the tumor cells." (PMID 29069865, 2017). "Recent studies have also shown that TGF-β1 can regulate the expression of S100A4, and cancer cells invasion mediated by TGF-β1 could be inhibited by S100A2 silence, indicating that S100A4 might be the molecular target of TGF-β1 in tumor metastasis." (PMID 24885536, 2014). "Thus, a tumor with high RAGE expression does not necessarily need high endogenous S100A4 expression levels to activate the receptor." (PMID 24952599, 2014). "On the one hand, this probably facilitates survival of tumor cells by elevating the expression of S100A4 and other osmoadaptive genes like AR, HSP70, or BGT-1; on the other, the elevated S100A4 expression may also increase the metastatic activity of the tumor cells." (PMID 25152734, 2014). "By discovering the mechanism in this signalling transduction pathway, we propose that a combined treatment of TG2 inhibition with the inhibition of key signalling targets e.g. PKCα could be more promising therapeutic approach for the treatment of S100A4 and TG2 containing tumours." (PMID 23469180, 2013). "Therefore, S100A4 could participate in controlling basal membrane degradation of EC and in the destruction of the ECM to facilitate the invasion of tumor cells." (PMID 24023743, 2013). "The aim of the present study was to investigate whether S100A4 induces expression of ephrin-A1 and osteopontin in NSCLC, and to characterize the expression of these molecular markers in primary tumor tissue from prospectively recruited patients undergoing curative surgery for NSCLC." (PMID 22853000, 2012). "Taken together, these results indicate that the biological function of S100A4 is cell type-dependent, and possibly, S100A4 may not play a pro-metastatic role in all tumor types." (PMID 22853000, 2012). "Hence, S100A4-expressing tumor cells have a much stronger metastatic ability than their S100A4-negative counterparts." (PMID 23166536, 2012). "While other members of this family, such as S100A4, S100A7 and S100A13, have been shown to participate under similar conditions, this discussion focuses on S100A8/A9's role in tumorigenesis by reviewing the effects of S100A8/A9 on tumor cells or vascular endothelial cells." (PMID 22685372, 2012). "Depletion of PMN-MDSC resulted in a very significant inhibition of tumor cell dissemination (85% reduction in the draining lymph node, 74% in the lung, 40% reduction in the incidence of cutaneous tumors) and EMT (68% reduction in S100A4+ cells and 70% reduction in vimentin+ cells)." (PMID 21980263, 2011). "Notably, S100A4 is not tumorigenic per se as evidenced by the failure of transgenic mice overexpressing S100A4 to develop tumours, but instead acts as a potential inducer of metastasis in a given tumorigenic background." (PMID 15900299, 2005). "Although it is not clear what leads to the focal overexpression of S100A4, it may be resulted from local demethylation or hypomethylation, one of the early events in tumour development." (PMID 16265347, 2005). "Furthermore, CTLA4+ T cells secrete S100A4, which induces a stem-like phenotype in TNBC cells, while CD44 has been recognized as a stem cell marker in BC that binds multiple ECM components, notably hyaluronic acid (HA), modifying tumor behavior through co-receptor interactions." (PMID 41602418, 2026).
tumor (continued). "Exosomal S100A4 derived from highly metastatic HCC cells (HMH) enhanced the stemness and metastatic potential of low metastatic HCC cells (LMH), indicating that exosomes could mediate interplay within tumor ecosystem, affecting phenotypical intratumor heterogeneity." (PMID 34035222, 2021). "However, whether S100A4 can promote tumor development by regulating autophagy has not been determined." (PMID 29449540, 2018). "However, S100A4 expression was not related to distant metastasis (RR = 1.23, 95% CI = 0.94–1.62, P = 0.13, random effects model) in 3 eligible studies or tumor histology (RR = 1.21, 95% CI = 0.99–1.47, P = 0.07, random effects model) in 7 eligible studies." (PMID 26903691, 2016). "Thus, it was suggested that S100A4 may be necessary for dissemination to distant metastatic sites rather than for local tumor invasion, and it could possibly be a good biomarker for metastasis and prognosis." (PMID 23166536, 2012). "Interestingly, S100A4+ cells were found specifically in the periphery of tumor nodules." (PMID 21980263, 2011). "Moreover, no metastases were detected in the lungs of the S100A4(−/−), that finally grew tumours." (PMID 15900299, 2005). "Thus, no staining for S100A4 was seen in the tumours produced by the 8Neu cell line." (PMID 14710237, 2004). "In a separate study, co-transplantation experiments in vivo with THP-1 and 4T1 cells showed that S100a4 WT, but not S100a4 knockout (KO), THP-1 TAMs promote tumor growth in vivo." (PMID 40078995, 2025). "The negative impact of tumor organoid factors on the contractile SMC phenotype was further supported by an increase in the SMC proliferation rate and the upregulation of S100A4." (PMID 38339292, 2024). "Immunohistochemical analysis demonstrated the positive expression of S100A4, CDK4, MDM2, CD34, and Vimentin, along with the negative expression of Leptin, confirming the tumor’s high aggressiveness and malignancy." (PMID 39591300, 2024). "For CC-3 immunostaining, there was a trend toward more positive cells in S100a4-Cre; Ext1f/f compared to the controls in MC38 and Pan02 tumor cells, but the difference was not significant." (PMID 36809261, 2023). "An interaction between S100A4 and NMIIA was observed in lysates from KS-1 cells, and by using in situ PLA we confirmed that this interaction was mainly in the cytoplasm of tumor cells, particularly in non-Ps perinecrotic lesions." (PMID 35392912, 2022). "Crosstab analyses showed that exosomal S100A4 level was significantly correlated with serum alpha-fetoprotein (AFP) level, tumor size, vascular invasion, and TNM stage, but not with BCLC stage." (PMID 34035222, 2021). "However, this increase did neither correlate with debulking efficiency nor with residual tumor burden or prognosis, suggesting that this phenomenon could be caused by an unspecific and transient release of MACC1 and S100A4 mRNA into the blood, possibly due to tissue damage during surgery." (PMID 30927479, 2019). "In our study, we evaluated ccRCC tumor tissues by immunofluorescence staining of common EMT markers (CDH1, CK18, CK19, VIM, S100A4) and stratified patients to EMT positive and EMT negative groups." (PMID 27549611, 2016). "In this study, EMT-related changes in the expression of E-cadherin, β-catenin and S100A4 were more severe in the invasive margin than in the tumor center and EMT changes in the invasive margin, but not the tumor center, had prognostic significance." (PMID 23783026, 2013). "Interestingly, 5 existing markers (ACTA2, VIM, S100A4, POSTN, PDPN) are not specific for any of the 9 tumor types we studied." (PMID 36263012, 2022).
tumor (continued). "In our study, although S100A4-dependent MMP-9 expression was inhibited by BITC treatment in vivo, S100A4/MMP-9 could not exert its inhibitory effect on tumor metastasis, which might be due to changes in the environment inside the tumor." (PMID 30970087, 2019). "Hcc-3 may have originated from a CD56+/CK19+/EpCAM+ microscopic nodule, and hcc-2 from a S100A4+/CK19−/CD56− microscopic nodule; the majority of the tumour mass (which was negative for CD56 and S100A4 but expressed EpCAM and CK19) generated hcc-1, the most aggressive of the three cell populations." (PMID 21731718, 2011).